REN (renin)
Diseases named in the same sentence as REN in open-access papers (continued):
Sharing a sentence is not in itself a finding about the gene and the disease.
Hypertension (continued). "The renin-angiotensin system, classically known for its involvement in the regulation of blood pressure, has been a target in the development of drugs for the treatment of hypertension." (PMID 21247419, 2011). "Moreover, glomerular hypoperfusion results in an increased release of renin, leading to deterioration of arterial hypertension." (PMID 22031827, 2011). "Importantly, after a few days, renin release by the stenotic kidney returns to normal values, and hypertension becomes dependent on extracellular (and blood) volume expansion and independent from the RAS." (PMID 21251296, 2011). "If sodium and water depletion is induced, hypertension becomes newly renin-dependent." (PMID 21251296, 2011). "Moreover, long-term treatment with these compounds induces pseudoaldosteronism with hypertension, hypokalemia, and eventual suppression of renin and aldosterone production." (PMID 21712989, 2011). "Plasma aldosterone and renin levels may be measured in patients with hypertension and/or hypokalemia." (PMID 21806824, 2011). "In addition, perinatal inhibition of the renin-angiotensin system impairs renal function and induces salt-sensitive hypertension in normotensive animals but prevents hypertension in spontaneously hypertensive rats." (PMID 20804606, 2010). "Although inconclusive, current evidence suggests that the renin-angiotensin system may be involved in hypertension." (PMID 20537141, 2010). "While the renin-angiotensin system may be the primary contributor to renal salt and water retention during the early phase of hypertension, both the sympathetic nervous and renin-angiotensin systems contribute importantly to sustained hypertension." (PMID 20804606, 2010). "This is of great interest, since renin is known as a rate limiting protein of Renin-Ang-II system (RAS) and Ang II is the effector peptide that directly binds to blood vessels, causes vasoconstriction and leads to systemic hypertension in humans." (PMID 19436702, 2009). "Certainly, ACEI may be less effective in Blacks, in whom the incidence of high renin hypertension is lower than in Caucasian population." (PMID 19622160, 2009). "Thus, this review highlights and discusses the roles of probiotics on the modulation of lipid profiles, insulin, renin and sexual hormones in the effort to reduce hypertension." (PMID 19865517, 2009). "Further studies to evaluate the effects of aliskiren on cardiovascular outcomes and target organ protection are ongoing and will provide important new data on the role of direct renin inhibition in the management of hypertension and other cardiovascular disease." (PMID 27713228, 2009). "Visceral obesity, insulin resistance, oxidative stress, endothelial dysfunction, activated renin-angiotensin system, increased inflammatory mediators, and obstructive sleep apnea have been proposed to be possible factors to develop hypertension in the metabolic syndrome." (PMID 18416854, 2008). "These associations were independent of systolic function, hypertension, the presence and severity of chronic kidney disease, the use of renin-angiotensin inhibitors and other potentially confounding variables." (PMID 18500986, 2008). "Obese individuals exhibit an activated renin-angiotensin system, which induces hypertension." (PMID 18416854, 2008). "However, despite the challenges of designing renin inhibitors, the enzyme remains a promising target for the development of novel treatments for hypertension." (PMID 18582379, 2008). "Although androgens may be involved in some forms of hypertension by up-regulating the renal renin-angiotensin system, data suggest an effect of testosterone on the vascular control mechanisms of blood pressure." (PMID 20066139, 2008). "It will therefore be of major interest to see the effect of spironolactone in hypertension and whether such an effect is more prominent in subjects with a high aldosterone: renin ratio." (PMID 17490489, 2007).
Hypertension (continued). "Spironolactone has been shown to reduce QT dispersion in chronic heart failure and it is of interest to investigate whether this is also the case in hypertension and whether such an effect is more prominent in subjects with a high aldosterone: renin ratio." (PMID 17490489, 2007). "One speculation is that the juxtaglomerular cells become injured and thus the renin-angiotensin system also is impared, which may prevent hypertension." (PMID 16928270, 2006). "Initially, DNA samples from 27 patients with low renin/low aldosterone hypertension were examined." (PMID 15661075, 2005). "However, the hypertension in this patient could also reflect an excessive salt supplementation, which would explain the suppressed renin level." (PMID 40569305, 2026). "Thus, the current recommendation by the Endocrine Society is that all individuals with hypertension be screened for PA by measuring serum or plasma aldosterone concentration and plasma renin concentration or activity to calculate the aldosterone-to-renin ratio (ARR)." (PMID 41601940, 2026). "Furthermore, renal hypoperfusion and ischemia may activate the renin–angiotensin–aldosterone system, contributing to persistent hypertension even after CoA repair." (PMID 39821132, 2025). "Also, IR-related hyperinsulinemia may affect the activity of sympathetic nervous system, or increase the activation of the renin-angiotensin-aldosterone system, resulting in hypertension." (PMID 39819581, 2025). "Additionally, the activation of the renin-angiotensin system contributes to hypertension." (PMID 40548446, 2025). "Additionally, miRNAs play important roles in regulating MetS components, as follows: obesity through adipogenesis and lipogenesis; hypertension through regulation of the renin–angiotensin system and vascular tone; and dyslipidemia by modulating lipid metabolism." (PMID 40565979, 2025). "There is a bridge between hypertension and anxiety, and the mechanism of its occurrence may be related to activation of the renin-angiotensin system, thrombosis, inflammation development, increased ion reabsorption, aortic atherosclerosis, and endothelial dysfunction vascular reactivity." (PMID 40153757, 2025). "However, considering the high prevalence of renin–angiotensin system inhibitor (RASi) usage for hypertension among LTCF residents, cautious administration is warranted, as concurrent trimethoprim–sulfamethoxazole and RASi use has been associated with an increased risk of sudden mortality." (PMID 41009853, 2025). "This systematic review demonstrates that direct renin inhibition with aliskiren provides BP-lowering efficacy comparable to ACEi and ARBs, with potential additional benefits in select subgroups such as patients with obesity-related hypertension and those with advanced microalbuminuria." (PMID 41409925, 2025). "Similarly, apparent mineralocorticoid excess, an autosomal recessive disorder caused by mutations in the HSD11B2 gene encoding 11β-hydroxysteroid dehydrogenase type 2, presents with juvenile-onset severe hypertension, low renin and aldosterone, hypokalemia, and metabolic alkalosis." (PMID 40493279, 2025). "Therefore, astaxanthin may attenuate hypertension via reducing blood pressure, mitigating oxidative stress, improving mitochondrial functions, and inhibiting the overactivation of the renin–angiotensin–aldosterone system in serum." (PMID 40143179, 2025). "However, after menopause, the decline in estrogen levels weakens its cardiovascular protective effect, reduces its inhibition of the renin–angiotensin–aldosterone system (RAAS), and weakens its role in maintaining vasodilation and endothelial function, increasing the risk of hypertension." (PMID 40610956, 2025).
Hypertension (continued). "However, the activity of the angiotensin-converting enzyme 2 was associated with the degree of calcification but not the severity of stenosis, indicating that further research was urgent for the role of the valvular renin-angiotensin system in CAVD pathogenesis beyond its effects on hypertension." (PMID 40356984, 2025). "The pathophysiology of hypertension in DM involves maladaptive physiological changes, including dysregulation of the autonomic nervous system, immune system alterations, heightened activation of the renin‐angiotensin‐aldosterone system (RAAS), and adverse environmental exposure." (PMID 40600774, 2025). "Indirect mechanisms may involve activation of the renin–angiotensin–aldosterone system, hypertension, adipokines leading to renal lipotoxicity, and the nucleotide-binding oligomerization domain-like receptor pyrin domain 3 inflammasome, all of which can impact renal function." (PMID 41327700, 2025). "It is assumed that hypertension in patients with CoA likely stems from multiple biological mechanisms, such as innate morphological abnormalities of the aortic wall, residual pressure gradients following repair, and dysregulation of the renin-angiotensin and baroreceptor systems." (PMID 39821132, 2025). "The synergistic effect of hypertension and elevated TyG-BMI may exacerbate vascular remodeling by activating the renin-angiotensin system and increasing sympathetic nervous system activity, and the thinner vascular walls in women are more susceptible to such damage." (PMID 41199859, 2025). "In addition, the ACE2 receptor is down-regulated during the infection process, resulting in the hyperactivation of the classical renin–angiotensin–aldosterone system pathway and/or hypertension of the sympathetic nervous system in the blood–brain barrier (sympathetic hypertonia)." (PMID 39860493, 2025). "In patients with low-renin hypertension, the antihypertensive effects of captopril are attributed to the induction of the release of endogenous vasodilating prostaglandins, while in normal renin hypertension, a prime antihypertensive mechanism is based on inhibition of the renin-angiotensin system." (PMID 40806350, 2025). "The pathophysiology of hypertension is closely linked to disorders that lead to the development of CKD such as endothelial dysfunction, deregulation of sodium metabolism, activation of the sympathetic nervous system, and increased activity in the renin–angiotensin–aldosterone system." (PMID 40429594, 2025). "In addition, a Spanish study of more than 12,000 patients observed that hypertension among patients treated with angiotensin-converting enzyme inhibitors or renin-angiotensin-aldosterone blockers or angiotensin II receptor blockers was significantly associated with lower all-cause mortality." (PMID 40678139, 2025). "This systematic review evaluated the comparative efficacy of direct renin inhibitors, primarily aliskiren, versus angiotensin-converting enzyme inhibitors (ACEi) and angiotensin receptor blockers (ARBs) in the management of hypertension across varied patient populations." (PMID 41409925, 2025). "Additionally, it may inhibit renin activity, thereby decreasing cardiovascular risk by reducing activation of the renin–angiotensin–aldosterone system (RAAS), which plays a key role in the development of hypertension." (PMID 41010515, 2025). "Additionally, elevated levels of inflammatory cytokines such as IL-6 and TNF-α may activate both the hypothalamic–pituitary–adrenal axis and the renin-angiotensin-aldosterone system, further promoting hypertension and cardiovascular pathology." (PMID 41323632, 2025). "Moreover, the absence of the PRR in the collecting ducts impairs intrarenal Ang II formation and increases urinary renin activity during experimental hypertension, suggesting that PRR binding to prorenin or renin enhances intratubular Ang II, promoting Na+ reabsorption, impacting blood pressure." (PMID 40362413, 2025).
Hypertension (continued). "In Black populations, unique features such as low-renin hypertension partly driven by genetic polymorphisms like the T594M mutation of the epithelial sodium channel may contribute to higher BPV and a greater burden of hypertension-related complications." (PMID 41541854, 2025). "Additionally, hypertension patients may experience tinnitus as a result of taking medications that stimulate the renin-angiotensin system or raise peripheral vascular tone (β-blockers)." (PMID 40642015, 2025). "As in FH1, autosomal dominant inheritance with incomplete penetrance has been hypothesised, as many individuals are heterozygous and some cases of patients with a normal aldosterone/renin ratio or spontaneous improvement of hypertension with increasing age have been observed." (PMID 40540150, 2025). "Obesity is known to induce resistance related to adipose tissue, affecting the renin-angiotensin system and leading to increased intra-abdominal and intravascular fat, sodium retention, and sympathetic nervous system activation, all contributing to obesity-related hypertension." (PMID 39899164, 2025). "Interestingly, the higher BP was linked to lower plasma renin activity, indicating that hypertension after preterm birth is likely not mediated by the renin–angiotensin system (RAS), contrary to previous proposals." (PMID 39457178, 2024). "Previous studies suggested that a higher prevalence of hypertension in men than women might result from the androgen-specific effects of increased BP through the renin-angiotensin system or the potentially protective effects of estrogen on the vasculature and the sympathetic nervous system." (PMID 39621934, 2024). "Therefore, there have been reports of kidney transplantation: in two adult patients with AME and renal failure, the clinical symptoms of AME disappeared after kidney transplantation, spironolactone treatment was discontinued, and both low renin hypertension and hypokalemic alkalosis were alleviated." (PMID 39931437, 2024). "In male SHR, genes involved in inflammation, renin-angiotensin signaling, and sympathetic processes (Il1b, Agt, and adrenergic receptor subunits Adra1b and Adrb2) were differentially expressed across multiple organs and time points throughout the progression of hypertension." (PMID 39514592, 2024). "Despite an absence of relationship between the REN (rs5707) and REN (rs2368564) polymorphisms in a central China population study, Mexican women showed SNPs of the REN gene with strong association to an increased risk of hypertension development." (PMID 38411777, 2024). "By inhibiting XO, HS extract may be useful in managing hyperuricemia, an index of gout, and preventing downstream events, including increased reactive oxygen species production, activation of the renin/angiotensin pathway, and inactivation of bradykinin, which links hyperuricemia to hypertension." (PMID 38397511, 2024). "Excess body weight may lead to hypertension through impaired structural and functional renal activity, increased cardiac output, arterial and aortic stiffening due to the activation of sympathetic activity and the renin-angiotensin-aldosterone system (RAAS)." (PMID 39666692, 2024). "Moreover, by analysing the data obtained in the Framingham study, it was concluded that the renin-angiotensin system (RAS), characterised by a high concentration of the renin-angiotensin ratio in serum, has an increased prevalence of shortening TL in patients with arterial hypertension." (PMID 39062937, 2024). "The renin-angiotensin system may serve as a pivotal link between hypertension and epilepsy." (PMID 39606700, 2024). "Therefore, some researchers believe that hypertension in patients with NCS may be due to increased pressure in the LRV caused by LRV entrapment, which stimulates the increased release of renin." (PMID 39540002, 2024).
Hypertension (continued). "Thus, 11β-OHD is characterized by increased serum concentrations of 11β-deoxycorticosterone, 17-hydroxyprogesterone (17-OHP) and androgens, resulting in hypertension with low renin levels, hypokalemia and genital ambiguity in affected individuals with a 46,XX karyotype." (PMID 37486441, 2024). "At present time, for the treatment of hypertension, there are a number of active angiotensin II (AT II) receptor antagonists (candesartan, losartan, and so on) which are available representing therapeutic effect in the interference of the renin-angiotensin-aldosterone system to lower the BP." (PMID 38410720, 2024). "Primary aldosteronism (PA) is a spectrum of diseases caused by excess renin-independent secretion of aldosterone; its manifestations range from normotension to severe hypertension, with or without hypokalemia, and it results in increased cardiovascular morbidity and mortality." (PMID 39301312, 2024). "Additionally, it is widely known that obese individuals with obstructive sleep apnea syndrome endure intermittent episodes of hypoxia and/or hypercapnia, triggering the SNS and the renin–angiotensin–aldosterone system, which significantly contribute to hypertension." (PMID 39457606, 2024). "Many studies, including some performed in the UK, have demonstrated that plasma renin level is lower in hypertensive black individuals compared with white subjects although the evidence that aldosterone-associated hypertension is more common in African origin subjects is lacking." (PMID 37964158, 2024). "This could implicate radically different levels of pressor pathways activation (renin increase, afferent sympathetic nerve activation and hypertension, tissue hypoxia, inflammation, injury, and fibrosis), resulting in different outcomes of invasive RAS treatment." (PMID 39274236, 2024). "In addition, another potential mechanism of hypertension may be the increased sympathetic tone and increased renin-angiotensin system (RAS)." (PMID 39771076, 2024). "It is hypothesized that oral contraception may contribute to hypertension through a ‘first-pass’ effect, where oral estrogens induce hepatic production of the renin substrate, angiotensinogen, leading to an increase in angiotensin I which is in turn converted to angiotensin II." (PMID 38846628, 2024). "Finally, visceral fat expansion derived from obesity may directly compress the kidney thereby activate the sympathetic nerve system and renin–angiotensin–aldosterone system to result in hypertension." (PMID 39598197, 2024). "Although it is speculated that androgens play a role in affecting natriuresis pressure as well as renin–angiotensin system which makes liability of hypertension more common in males than females yet, females have other risks along their life that expose them to hypertension." (PMID 37305216, 2023). "Obesity and insulin resistance are common in patients with hypertension and may contribute to hypertension via multiple potential mechanisms, including activation of the sympathetic nervous system and the renin-angiotensin-aldosterone system, oxidative stress, and endothelial insulin resistance." (PMID 37789259, 2023). "The resulting dataset provides novel insight into cell-specific molecular changes that occur within the ARC in response to DOCA-salt, which may represent novel contributors to or consequences of hypertension and hypermetabolism occurring in this model of low-renin hypertension." (PMID 37293629, 2023). "These multiplied viral entry points might be the reason behind the high morbidity and mortality in COVID‐19 patients with hypertension or diabetes because patients having hypertension and/or diabetes take drugs targeting the renin‐angiotensin system (RAS) to lower blood pressure and protect kidney." (PMID 37773723, 2023).